BRAF (B-Raf proto-oncogene, serine/threonine kinase)
Diseases named in the same sentence as BRAF in open-access papers (continued):
Sharing a sentence is not in itself a finding about the gene and the disease.
tumor (continued). "The common view was that larger tumour size, the presence of vascular invasion, an abnormal contralateral thyroid lobe after hemithyroidectomy, aggressive histopathology and positive BRAF V600E were factors that would increase the intensity of follow‐up." (PMID 36738092, 2023). "Again, taking a projection onto the 2D plane having fixed the biomarker BRAF yields the basket of different tumour types labelled by BRAF." (PMID 37217528, 2023). "It would be helpful to routinely analyze the activity of BRAF and downstream signaling pathways to evaluate the vulnerability of tumor cells." (PMID 36856908, 2023). "In line with the mutual exclusivity of BRAF and KRAS mutations, we only detected the BRAF V600E mutation in the analysis of the initial tumor." (PMID 36967525, 2023). "CRC patients in the high ARG_score group tended to have a shorter RFS than that in the low ARG_score group (P < 0.001), as demonstrated by the results for age, sex, tumor location, TNM stage, and KRAS and BRAF mutations." (PMID 37938164, 2023). "RAS mutations were present in 3.0% of tumors, while BRAF, K-RAS, and N-RAS mutations were found in 3.0%, 29.7%, and 25.9% of tumor tissues, respectively." (PMID 37289436, 2023). "We measured changes in tumor volume for >50 d in mice treated with encorafenib (BRAF inhibitor) ± panitumumab (EGFR inhibitor) ± celecoxib (COX2 inhibitor)." (PMID 36759733, 2023). "Second, BRAF and FGFR1 mutations were mutually exclusive, as only one tumour presented both hits (case #23)." (PMID 38066305, 2023). "The DDAH2 gene showed more differential methylation (hypermethylation) in tumor tissue in BRAF wild-type tumors compared to the mutant group." (PMID 36975440, 2023). "BRAF mutations were predominantly found in CMS1, but nevertheless, 27 out of 53 BRAF mutant tumours were distributed among CMS2-4." (PMID 37666855, 2023). "Corticocotroph PitNET cells harboring the BRAFV600E mutation undergo a more significant reduction in hormone secretion when treated with BRAF inhibitor Vemurafenib, compared to tumor cells with wild-type BRAF." (PMID 37958702, 2023). "Tumor regression from the combined dual MAPK pathway blockade with BRAF and MEK inhibitors was also confirmed in BT40 PDoX, which are described in greater detail below." (PMID 37920169, 2023). "This distinct phenotype plasticity of tumor cells in response to BRAF/MEK inhibition is partly regulated epigenetically—an in-depth review of the epigenetic mechanisms underlying the drug resistance is available elsewhere." (PMID 37834284, 2023). "Microsatellite instabilities (MSI) and somatic mutations in BRAF and RNF43 were enriched in both CMS1 and right-sided tumours (FDRmol < 0.05, hypergeometric test)." (PMID 37666855, 2023). "We next investigated the impact of tumor suppressor gene inactivation on the growth of BRAF V600E- and EGFR L858R-driven lung tumors and compared tumor suppressor effects across all four oncogenic alleles." (PMID 37828026, 2023). "Thanks to the availability of BRAF inhibitors, BRAF p.V600E has been exploited as a therapeutic target in many neoplasms." (PMID 38067388, 2023). "Activation of the BRAF gene in NSCLC has been associated with uncontrolled cell proliferation and resistance to apoptosis, contributing to tumor growth." (PMID 37444584, 2023). "In BRAFV600E, valine (V) is substituted by glutamic acid (E) at amino acid 600, resulting in activating BRAF with subsequent tumor growth and spread." (PMID 36900367, 2023). "The tumor cells harbored the BRAFV600E mutation known to be associated with PTC and presented enrichment of genes involved in cancer and BRAF signature like the thyroid of Borealin+/− mice." (PMID 37964961, 2023). "Neoadjuvant BRAF-directed therapy reduced tumor size, extent of surgery, and surgical morbidity score." (PMID 36762947, 2023).
tumor (continued). "Overall, these data provide evidence for a tumor cell-intrinsic role of BRAF/MAPK pathway inhibition in promoting tumor immune response." (PMID 36702949, 2023). "The tumour sample in PanSPS_044 (III-1) showed loss of expression for MLH1/PMS2 and was BRAF mutated and MGMT methylated." (PMID 36270769, 2023). "BRAF immunohistochemical staining were performed in 17 metastatic lymph nodes with sufficient tumor tissues, and 6 were positive." (PMID 37454141, 2023). "The combination of a BRAF inhibitor and miR-200c reportedly prevents drug resistance, boosts the host immune response against the tumor, and makes anti-tumor treatment effective at decreased dosages." (PMID 37446039, 2023). "This cytokine is produced by TAMs to promote tumor growth in vivo and stimulate tumor cell invasion in vitro, thus acting as a source of resistance to BRAF and MEK inhibitors." (PMID 37152280, 2023). "To assess the effectiveness of SJF-0628 in a broader set of cancer cells representative of diverse biochemical and genetic backgrounds, BRAF genotype, and tumor types, we selected several BRAF V600E-containing CRC and TNBC cell lines." (PMID 38136350, 2023). "The leading biomarkers that led to treatment recommendations were tumor mutational burden‐high (TMB‐H) (n = 32), ERBB2 amplification (n = 24), BRAF V600E (n = 16), and BRCA1/2 alterations (n = 32)." (PMID 36251535, 2023). "Among the primary tumor gene mutations, 49 (46.7%) patients had a RAS mutation, 48 (45.7%) patients were RAS wild-type, 4 (3.8%) patients had a BRAF mutation and 93 (88.6%) patients were BRAF wild type." (PMID 36937443, 2023). "The recent authorization for a tumor-agnostic approach that employs a BRAF and MEK inhibitor combination marks a significant leap forward in precision medicine." (PMID 38001751, 2023). "Here, we present a metastatic ATC patient with PD-L1 positive (tumor proportion score of 60%) tumor and NRAS Q61R/BRAF D594N mutations, who progressed on PD-1 antibody sintilimab plus angiogenesis inhibitor anlotinib." (PMID 37122752, 2023). "The final evaluation of tumor volume and weight and further analysis of tumors were performed after 18 or 30 days of PK5L1940 or BRAF tumor growth, respectively based on tumor size." (PMID 37415974, 2023). "When it was combined with the BRAF inhibitor vemurafenib, more enhanced tumor inhibition was discovered through the induction of ferroptosis." (PMID 37373523, 2023). "When the patient has an MSS, RAS and BRAF wild-type tumour, the next important question to answer is the location of the primary lesion." (PMID 37377686, 2023). "Because the tumor harbored a BRAFV600 mutation, combination of vemurafenib (BRAF inhibitor) and trametinib (MEK inhibitor) was added to treatment strategy." (PMID 37448517, 2023). "In patients with RAS/BRAF mutant tumours, bevacizumab and its analogues offer the only viable choice of MCA." (PMID 36674640, 2023). "The BRAF V600-specific inhibition of tumor growth across various tumor entities is a prime example of personalized cancer treatment and depends on the availability of diagnostic biomarkers with predictive power for drug response." (PMID 36472769, 2023). "Raised KCNMA1 then acts to repolarize the membrane potential and sustain p-BRAF levels, which promotes tumor cell proliferation." (PMID 36763212, 2023). "Tumours demonstrating the MaP pattern of stromal invasion more frequently harboured core MAPK pathway mutations (KRAS, BRAF, NRAS)." (PMID 37169775, 2023). "This article evaluates the prognostic effect of primary tumor location in the Belgian population to determine the role of biomarker status (MMR, BRAF, and RAS mutational status)." (PMID 37071802, 2023). "Although a variety of hallmark signature changes were observed in subtypes defined by BRAF mutation in SKCM and THCA, only a small portion were consistently observed across these two tumor types." (PMID 36860655, 2023).
tumor (continued). "From a biological standpoint, CRC is a heterogeneous disease in which biological covariates such as CIMP, KRAS/BRAF mutation, MSI and tumor location complicate treatment response and patient outcomes." (PMID 37296894, 2023). "The loss of p16, mostly related to a CDKN2A deletion, abrogates the senescent features of tumor cells stably overexpressing altered BRAF." (PMID 36831610, 2023). "For these patients, BRAF-directed therapy offered a marked reduction in tumor size and extent of surgical resection." (PMID 36762947, 2023). "BRAF, NRAS, TG, TTN, and HRAS were the most frequently mutated genes in the early and late stages of the tumor; however, other genes were found to be more frequently mutated in the late stage." (PMID 37854594, 2023). "We found the majority of BRAF mutations in CMS1 and observed a co-occurrence between CMS2, left-sided tumours and amplifications in chr20q." (PMID 37666855, 2023). "A Clinical Laboratory Improvement Amendments–certified targeted sequencing assay was used to analyze tumor resection specimens, with a focus on BRAF V600E alteration." (PMID 37589977, 2023). "Sensitivity to BRAF- and mitogen-activated protein kinase (MEK) inhibitors varies depending on BRAF mutations and tumor cell types." (PMID 36856908, 2023). "Nevertheless, we observed that the concomitant BRAF inhibition counteracts the PMN‐MDSC tumor infiltration induced by anti‐m‐VEGFA treatment." (PMID 37183363, 2023). "Local molecular tumour profile showed 91 (49%) RAS mutant tumours, 8 (4%) BRAF V600E tumours and 6 (3%) MSI‐H/dMMR tumours, although MMR status was not fully completed in the whole cohort." (PMID 37097008, 2023). "In this sense, patients with BRAF-mutant tumours, brain metastases, or PD-L1-negative status appear to obtain a greater benefit with nivolumab–ipilimumab versus single-agent immunotherapy." (PMID 37404764, 2023). "BRAF-inhibitor monotherapy in BRAFV600E-mutated CRC has low response rates, which is linked to incomplete inhibition of MAPK signaling in tumor cells." (PMID 37296986, 2023). "Beyond these widely approved biomarkers, primary tumor location has been reported to be predictive of response to these therapies in the front-line setting of all RAS/BRAF wild-type tumors." (PMID 37133732, 2023). "To summarize, this study demonstrated a significant association between BRAF V600E AF and aggressive histopathological features of PTC as well as positive sentinel lymph nodes, indicating tumor spread to the central neck compartment." (PMID 38201541, 2023). "We clearly observed that loss of CXCR2 expression in tyrosinase-expressing cells where there was expression of mutant BRAF and loss of PTEN resulted in reduced tumor growth and lowered incidence of tumor formation." (PMID 37270599, 2023). "Others include tumor biomarkers, such as Kirsten rat sarcoma virus (KRAS) and V-Raf murine sarcoma viral oncogene homolog B (BRAF) mutations or microsatellite instability, which have implications for therapeutic selection." (PMID 38201497, 2023). "It frequently harbors BRAF, NRAS, or KIT mutations which influence both tumor development and treatment strategies." (PMID 37403699, 2023). "While the tumor suppressive effects of inactivating Pten, Rnf43, and Apc are consistent with previous data on these genes and/or related pathways in BRAF-driven lung cancer, the general decreases in magnitude relative to oncogenic KRAS were unexpected." (PMID 37828026, 2023). "The “Use with Caution” antibodies in this set include antibodies that bind the protein products of frequently altered cancer driver genes, such as the oncogenes MYC and BRAF and the tumour suppressors BRCA2 and VHL." (PMID 37169592, 2023). "In the context of melanoma, one report indicated that the expression of a tumour suppressor miR‐524‐5p in patients treated with BRAF inhibitors (BRAFi) serves as a positive prognostic indicator." (PMID 37735815, 2023).
tumor (continued). "SCH772984 inhibited the proliferation of BRAF or MEK inhibitor-resistant tumor cells by targeting the MAPK signaling pathway." (PMID 37976123, 2023). "Liquid biopsies, including those performed for circulating tumor DNA (ctDNA), are clinically used to detect RAS and BRAF mutations and perform comprehensive genomic profiling in CRC." (PMID 36900264, 2023). "The variables taken into consideration are BRAF, KRAS, NRAS mutations, the expression of fibronectin, CXCR4, and FAP in terms of intensity in both the primary tumor and metastases, and the number of metastases." (PMID 37892020, 2023). "A Comprehensive Somatic Variant Database (CSVD) was generated using the R programming language to include SNV, CNV, and structural variant data for each case, along with additional tumor-related information including tumor type and MSI and BRAF status." (PMID 38344144, 2023). "Here, it was shown that the suppression of histone deacetylases (HDACs) in combination with BRAF inhibitors also leads to increased apoptosis and decreased tumor growth in vivo." (PMID 36768289, 2023). "The Kaplan–Meier curves of DFS stratified by mutation status and tumor type revealed that DFS was worst for solitary CRC patients with RAS mutations (p = 0.020) or BRAF mutations (p = 0.023)." (PMID 37667167, 2023). "Accordingly, impaired anti-tumor activity was stated in male mice with elevated AR levels upon BRAF and MEK1/2 inhibition compared to female ones." (PMID 37686465, 2023). "The role of SMAD4, specifically during the process of BRAF-mutant tumor invasion, is less understood, partially owing to the limited number of model systems to monitor invasive behavior." (PMID 38136364, 2023). "If a higher tumor-derived BRAF p.V600E VAF is confirmed, it is understandable that cfDNA will also result in a higher VAF." (PMID 37958315, 2023). "We performed a pooled analysis of two‐phase II prospective trials to determine the role of rechallenge in third‐line mCRC patients with RAS/BRAF WT baseline circulating tumor DNA (ctDNA)." (PMID 36880426, 2023). "A low/intermediate tumor mutation burden (TMB) and microsatellite-stable status was found in BRAF mutated NSCLC patients." (PMID 37645429, 2023). "Co-targeting of COX2 with BRAF + EGFR promotes durable suppression of tumor growth in patient-derived tumor xenograft models." (PMID 36759733, 2023). "These proteins are restored by BRAF pathway inhibitors and thus enhancing immune response to tumor cells." (PMID 38136348, 2023). "In one report, miR-9 is shown to suppress the oncogene BRAF in thyroid papillary tumors and to reduce the growth of tumor cells when it is over-expressed." (PMID 36769076, 2023). "Mutant B-Raf proto-oncogene (BRAF) and RAS, and RET fusions were found to be the disease-causing alterations in about 80% of tumours in PTC: oncogenic BRAF (~60% of cases), H-RAS and N-RAS (~10%) and RET fusions (~5%)." (PMID 37207147, 2023). "The highest frequency of mutations detected was in the KRAS gene, in tumor biopsies and plasma samples, followed by mutations of the PIK3CA, NRAS and BRAF genes." (PMID 37176143, 2023). "It has been reported that RAFi resistant tumor cells acquire resistance due to increased CRAF activity via a transition from BRAF to CRAF-dominated bypass signaling, and the use of CRAFi in combination or pan-RAFi has been used to improve therapeutic efficacy." (PMID 37372381, 2023). "The post-operative pathology identified adenocarcinoma (pT4N2cM1) with KRAS/NRAS/BRAF wild-type MSS status in her tumor." (PMID 37681031, 2023).
tumor (continued). "As neoantigens have been found in BRAF V600E, KRAS, and PI3K, these mutated signaling proteins are targets of TSAs in tumor-specific immunotherapy." (PMID 38250858, 2023). "Recently, tumour progression and resistance to BRAF inhibition have also been shown to be due to autophagy promoted by the TFEB-TGF-β axis." (PMID 37627054, 2023). "7/8 (88%) methods found mutually exclusive alterations in KRAS, NRAS or BRAF as a predictive biomarker, from which one, two and four methods proposed this marker in conjunction with tumour sidedness, CMS and across all patients, respectively." (PMID 37666855, 2023). "In four patient-derived xenograft (PDX) CRC models harboring BRAF mutation (CR0004, CR0029, CR2179, CR6289), tunlametinib at dose of 1 mg/kg QD, responded (>79% TGI) with all the models exhibiting significant tumor growth suppression (p < 0.05)." (PMID 37808191, 2023). "Although ZEB1 is best known for triggering an EMT, we found that ZEB1-high in BRAF/Braf-mutant CRCs paradoxically correlated with low tumor budding and a reduced EMT signature, the opposite than in KRAS-mutant CRCs." (PMID 37870961, 2023). "The same co-dependency of p-BRAF and KCNMA1 levels was then also recognized in the HEK293T cell line, which was derived from non-tumor tissue with wt BRAF." (PMID 36763212, 2023). "Collectively, these results indicate that different oncogenes in the EGFR/KRAS/BRAF axis have dramatically different effects on tumor initiation and growth." (PMID 37828026, 2023). "We have found correlations between the mechanical properties (relative stiffening between normal and neoplastic ECM) of the ECM and patients’ clinical data, like age, sex, presence of protein activating mutations in BRAF and KRAS genes and tumour grade." (PMID 37500685, 2023). "In particular, BRAF and TERT promoter co-mutations were more commonly detected in male patients at an older age, that had a larger tumor size and were more prone to extra-thyroid invasion." (PMID 37046812, 2023). "Among patients with BRAF wild-type tumours, the confirmed ORR as assessed by investigators was 61% in the combination group versus 11% in the ipilimumab monotherapy group." (PMID 37404764, 2023). "In this study, we combined BRAF(V600E) knockin with various tumor suppressor knockouts in B cells to examine the origin and pathology of HCL, and hence constructed animal models mimicking human disease." (PMID 37543582, 2023). "Both intratumoural stroma and BRAF mutations are believed to promote EMT, suggesting that a tumour yielding one, or both, of these features exhibits not only epithelial features but also mesenchymal features." (PMID 37344790, 2023). "The tumor expression of MICA/B induced by BRAF and RAS has been observed in ATC and is responsible for the antitumor effects of NK cells." (PMID 38250858, 2023). "It has been postulated that BRAF and NRAS mutations are most likely due to clonal heterogeneity within the tumor." (PMID 36982192, 2023). "Pharmacological MEK inhibition completely abrogated tumor growth in BRAF mutant xenografts, whereas RAS-mutant tumors were only partially inhibited." (PMID 37808191, 2023). "These include molecular and genetic factors, such as microsatellite instability (MSI), BRAF and KRAS mutations, and tumor morphological factors, such as differentiation and lymphovascular invasion." (PMID 36800011, 2023). "The anti-tumor activity of tunlametinib as monotherapy was investigated in BRAF/KRAS mutant or wild type xenograft model." (PMID 37808191, 2023).